ATXN10 (ataxin 10)
Diseases named in the same sentence as ATXN10 in open-access papers:
ATXN10 is named in the same sentence as 68 diseases in open-access papers, as found by Europe PMC text mining. Sharing a sentence is not in itself a finding about the gene and the disease. The quoted sentences say what the papers report.
Ataxia (21 papers, 2011 to 2025). Ataxia refers to impaired coordination of voluntary muscle movement. "Atxn10 is a gene known for its role in cytokinesis and is associated with spinocerebellar ataxia (SCA10), a slowly progressing cerebellar syndrome caused by an intragenic pentanucleotide repeat expansion." (PMID 34970537, 2021). "The expansion of normally short sequence repeats in the ATXN10 gene is associated with the progressive neurodegenerative disease spinocerebellar ataxia." (PMID 28890930, 2017). "ATXN10 (Ataxin-10) encodes a protein that belongs to the family of ataxin proteins, which are implicated in neurodegenerative disorders such as spinocerebellar ataxia and may have roles in transcriptional regulation and RNA processing." (PMID 39058168, 2024). "Another example was the findings of a common repeat expansion locus in ATXN10, associated with both ataxia (SCA10) and parkinsonism, two unrelated phenotypes, suggesting that quite diverse phenotypes may share common genotypes." (PMID 35401394, 2022). "We analyzed the expression pattern of 28 ataxia risk genes and found that majority of them are highly expressed in PCs, while only a few of them, including elongation factor 2 (Eef2), ataxin-10 (Atxn10), nucleolar protein 56 (Nop56), are widely expressed in all cell types." (PMID 30690467, 2019). "RT-qPCR revealed that the mRNA transcription levels of four ataxia-related genes (ataxin 10 (Atxn10), protein phosphatase 2 regulatory subunit B beta (Ppp2r2b), protein kinase C gamma (Prkcg), and phospholipase D3 (Pld3)) were significantly changed in the Zfp212-KO Cb compared to those in the WT." (PMID 34815492, 2021). "Fourth, the ATXN10 repeat expansion in four siblings with cerebellar ataxia, seizures, and progressive dementia had an unusual repeat interruption of ATTCC, encompassing about 60% of the overall repeat expansion, which has not been reported to be associated with seizures." (PMID 28890930, 2017). "The function of ATXN10 remains largely unknown, but expanded ATTCT pentanucleotide repeats in intron 9 of the gene cause a rare form of spinocerebellar ataxia (SCA10) characterized by cerebellar ataxia and epilepsy." (PMID 29263841, 2017). "Large, non-coding pentanucleotide repeat expansions of ATTCT in intron 9 of the ATXN10 gene typically cause progressive spinocerebellar ataxia with or without seizures and present neuropathologically with Purkinje cell loss resulting in symmetrical cerebellar atrophy." (PMID 28890930, 2017). "Specifically, Ataxin-10 (ATX10) and Ataxin-3 (ATX3) are both responsible for different forms of spinocerebellar ataxia in humans, a type of neurodegenerative disease." (PMID 35482036, 2022).
spinocerebellar ataxia type 10 (19 papers, 2010 to 2026). Spinocerebellar ataxia type 10 (SCA10) is a subtype of type I autosomal dominant cerebellar ataxia (ADCA type I). "We chose myotonic dystrophy type 2 (DM2)-associated CCTGexp in ZNF9 and spinocerebellar ataxia type 10 (SCA10)-associated ATTCTexp in ATXN10 as representatives for intronic GC-rich and AT-rich repeats, respectively." (PMID 34389711, 2021). "The ATTCT pentanucleotide repeat expansion in intron 9 of the ataxin 10 (ATXN10) gene on chromosome 22q13.3 causes the neurodegenerative disorder spinocerebellar ataxia type 10 (SCA10)." (PMID 28423040, 2017). "Spinocerebellar ataxia type 10 (SCA10) is an autosomal dominant neurologic disorder caused by ATTCT expansion in the ATXN10 gene." (PMID 25666058, 2015). "Ataxin-10 is the disease-causing protein for Spinocerebellar ataxia type 10 (SCA10), the only disease known to be caused by pentanucleotide expansions." (PMID 25666058, 2015). "We have identified a large expansion of an ATTCT repeat within intron 9 of ATXN10 on chromosome 22q13.31 as the genetic mutation of spinocerebellar ataxia type 10 (SCA10)." (PMID 20548952, 2010). "Although mutations or repeat expansions in ATXN10 are associated with spinocerebellar ataxia type 10 (SCA10), the molecular function of the protein remains poorly understood." (PMID 41226456, 2025). "The mutation of spinocerebellar ataxia type 10 (SCA10) is a complex ATTCT pentanucleotide repeat within intron 9 of the ATXN10 gene that harbors cryptic repeat insertions." (PMID 32160188, 2020). "Three circRNAs were expressed in ATXN10 that maintains the survival of neurons, studied in the spinocerebellar ataxia type 10." (PMID 28842720, 2017). "Spinocerebellar ataxia type 10 (SCA10) is a rare, dominantly inheritedneurodegenerative disorder caused by a pentanucleotide (ATTCT) repeat expansion inintron 9 of the ATXN10 gene on chromosome 22q13.3." (PMID 29213474, 2016). "Spinocerebellar ataxia type 10 (SCA10) is a rare, inherited neurological disease caused by an expansion of the non-coding ATTCT pentanucleotide repeat in the ATAXIN 10 gene." (PMID 41653401, 2026). "McFarland and colleagues used PacBio to study the molecular bases of spinocerebellar ataxia type 10 (SCA10), a neurodegenerative disorder caused by the repeats of the “ATTCT” sequence in the intron 9 of the Ataxin 10 gene." (PMID 38785975, 2024). "Spinocerebellar ataxia type 10 (SCA10), an autosomal dominant cerebellar ataxia disorder, is caused by a non-coding ATTCT microsatellite repeat expansion in the ataxin 10 gene." (PMID 28423040, 2017). "Spinocerebellar ataxia type 10 (SCA10), an autosomal dominant cerebellar ataxia, is caused by the expansion of the non-coding ATTCT pentanucleotide repeat in the ATAXIN 10 gene." (PMID 24278426, 2013). "In addition, (ATTCT)n within an intron of the ataxin 10 (ATXN10) gene and (CCTG)n in the first intron of the zinc finger protein 9 (ZNF9)gene may lead to Spinocerebellar Ataxia 10 (SAC10) and Muscular dystrophy type 2 (DM2), respectively." (PMID 37570771, 2023).
Parkinsonism (7 papers, 2008 to 2025). Characteristic neurologic anomaly resulting from degeneration of dopamine-generating cells in the substantia nigra, a region of the midbrain, characterized clinically by shaking, rigidity, slowness of movement and difficulty with walking and gait. "For example, the variation of long tandem repeat loci in gene ATXN10 and C9orf71 is associated with Parkinson’s disease and amyotrophic lateral sclerosis, respectively." (PMID 36402991, 2022). "Genetic characterization of ATXN10 mutations reveals differences that may explain why some people develop Parkinson’s disease." (PMID 28890930, 2017). "Herein, we report a rare case with an ATXN10 repeat expansion in a patient clinically presenting with levodopa-responsive parkinsonism." (PMID 28890930, 2017). "First, we expand the phenotypic spectrum of the ATXN10 repeat expansion and report a patient with clinically defined Parkinson’s disease." (PMID 28890930, 2017). "Single-molecule sequencing paired with SMRT/Cas9 capture approach allowed us to characterize the genetic composition of the complete repeat expansion which revealed a novel phenotype-genotype correlation for Parkinson’s disease and ATXN10." (PMID 28890930, 2017). "We describe a rare case with clinically diagnosed Parkinson’s disease and an ATXN10 repeat expansion." (PMID 28890930, 2017). "The hypothesis is that the interruptions present in the SCA10 repeat expansion may serve as a “phenotypic modifier” of the genotype-phenotype correlation between ATXN10 and parkinsonism." (PMID 35401394, 2022). "In addition, No-Amp approach has been utilized to successfully sequence across C9orf72 and ATXN10 repeat expansion loci in patients with frontotemporal dementia or Parkinson’s disease, respectively." (PMID 31134132, 2019). "However, one affected individual presented with early-onset levodopa-responsive parkinsonism, and one family member carried a large repeat ATXN10 expansion, but was clinically unaffected." (PMID 28890930, 2017). "On the contrary, in our patient with early-onset levodopa-responsive parkinsonism we identified a slightly smaller ATXN10 repeat expansion of 1304 ‘common’ ATTCT repeats without the pentanucleotide interruptions ATTCC (III.8)." (PMID 28890930, 2017). "Second, the ATXN10 expansion in this case with Parkinson’s disease has virtually no repeat interruptions and presents the ‘purest’ repeat reported to date." (PMID 28890930, 2017).
Huntington disease (5 papers, 2011 to 2025). Huntington disease (HD) is a rare neurodegenerative disorder of the central nervous system characterized by unwanted choreatic movements, behavioral and psychiatric disturbances and dementia. "Interestingly, Ataxin-10 (Atxn10) and Huntingtin-associated protein 1 (Hap1), proteins associated with the neurodegenerative disease spinocerebellar ataxia 10 (SCA10) and Huntington’s disease, respectively, were identified as UBQLN2 interactors." (PMID 27164932, 2016).
autosomal dominant cerebellar ataxia (3 papers, 2013 to 2023). A clinically and genetically heterogeneous group of neurodegenerative diseases characterized by a slowly progressive ataxia of gait, stance and limbs, dysarthria and/or oculomotor disorder, due to cerebellar degeneration in the absence of coexisting diseases. "There was also no phenotypic crossover between those individuals who had expansions in ATXN10 and its linked disease, however this is likely because the manifestations of autosomal dominant spinocerebellar ataxia 10 are adult onset." (PMID 36701310, 2023).
dentatorubral-pallidoluysian atrophy (3 papers, 2011 to 2023). Dentatorubral pallidoluysian atrophy (DRPLA) is a rare subtype of type I autosomal dominant cerebellar ataxia (ADCA type I). "Genes that were part of this signature on the brain side were the TCF4, ATN1, PPP2R2B, ATXN10 and ATXN3, which are associated with neurodegenerative and developmental disorders such as Pitt-Hopkins Syndrome, Dentatorubral pallidoluysian atrophy, SCA12, SCA10 and SCA3." (PMID 27476530, 2016).
Joubert syndrome (2 papers, 2019 to 2021). Joubert syndrome (JS) is characterized by congenital malformation of the brainstem and agenesis or hypoplasia of the cerebellar vermis leading to an abnormal respiratory pattern, nystagmus, hypotonia, ataxia, and delay in achieving motor milestones. "The SCA protein ataxin 10 interacts with the ciliary proteins NPHP5 (nephronophthisis 5) and CEP290 (centrosomal protein 290), and a patient with Joubert syndrome had a mutation of ataxin 10 itself." (PMID 31299042, 2019). "This same study further identified ATXN10 as a Nephronophthisis (NPHP)- and Joubert syndrome (JBTS)-associated gene that indirectly interacts with the ciliary transition zone protein, NPHP5, near the base of the cilium." (PMID 34970537, 2021). "Atxn10 is also implicated in the ciliopathy syndromes nephronophthisis (NPHP) and Joubert syndrome (JBTS), which are caused by the disruption of cilia function leading to nephron loss, impaired renal function, and cerebellar hypoplasia." (PMID 34970537, 2021).
atherosclerosis (1 paper, 2021). A disease characterized by the build-up of fatty material and calcium deposition in the arterial wall resulting in partial or complete occlusion of the arterial lumen. "Taken together, these results indicate that Ataxin-10 inhibits endothelial cell activation and may serve as a promising therapeutic target for some vascular inflammatory-related diseases such as atherosclerosis." (PMID 34858081, 2021). "Thus, Ataxin-10 may be a potential target for preventing the progression of vascular inflammatory diseases, such as atherosclerosis." (PMID 34858081, 2021).
bipolar disorder (1 paper, 2007). A disorder of the brain that causes unusual shifts in mood, energy, activity levels and the ability to carry out day-to-day tasks. "For example, 10 genes among the 16 confirmed genes (Cacng2, Dnajc3, Dusp4, Gpc6, Mbp, Nov, Phf21b, Atxn10, Xbp1, and Zfyve28) have their human orthologs located within a 10 Mb region flanking the linkage markers for bipolar disorder, and thus merit further study." (PMID 18028544, 2007).
cardiac failure (1 paper, 2021). "Reflecting the highly localized expression pattern in the early heart, loss of ATXN10 resulted in severe pericardial effusion and ultimately cardiac failure." (PMID 34970537, 2021).
cervical cancer (1 paper, 2025). A primary or metastatic malignant neoplasm involving the cervix. "It was observed that in cervical cancer patient samples with elevated HIF-2α increased expression of Ataxin-10 occurs with a p-value of 0.0076." (PMID 41226456, 2025). "Herein, we investigate the interaction of HIF-2α with Ataxin-10, an intracellular protein involved in cell survival and differentiation, as well as the mechanism and the effects of this interaction in cervical cancer (HeLa) and glioma (U-87MG) cells." (PMID 41226456, 2025). "In addition, the analysis shows a significant correlation of Ataxin-10 mRNA levels and HIF-2 target genes (p = 0.014) in cervical cancer patient samples from the Gepia2 database." (PMID 41226456, 2025).
colon cancer (1 paper, 2022). "Moreover, the significant correlation between body weight loss and increased serum ataxin-10 levels suggests that ataxin-10 could be considered to be a potential biomarker for diagnostic and or prognostic purposes in colon cancer." (PMID 35326441, 2022).
glioblastoma (1 paper, 2025). The most malignant astrocytic tumor (WHO grade IV). "Specifically, we have shown that endogenous and overexpressed HIF-2α interact with Ataxin-10 in cervical and glioblastoma cells." (PMID 41226456, 2025).
leukemia (1 paper, 2024). A malignant (clonal) hematologic disorder, involving hematopoietic stem cells and characterized by the presence of primitive or atypical myeloid or lymphoid cells in the bone marrow and the blood. "Of the upregulated genes, Syne1, Atxn10 and Dach1 show activation as early as Day 11, while Ngp, Abca13, Adpgk, Mmp8 and Lcn2 were more significantly upregulated in the later stage, D14 neutrophils,which suggests a sequential activation in Camk1d + neutrophils during leukemia progression." (PMID 38730491, 2024).
pericardial effusion (1 paper, 2021). Fluid collection within the pericardial sac, usually due to inflammation. "Congenital loss of Atxn10 results in embryonic lethality around E10.5 associated with pericardial effusion and loss of trabeculation." (PMID 34970537, 2021).
progressive ataxia (1 paper, 2020). "Last, there were three genes (ITPR1, ATP8A2, and ATXN10) that overlapped with a gene set of hereditary progressive ataxia (n = 59) and the SN-meta-DEGs (p = 0.4320)." (PMID 33390883, 2020).
SARS-CoV infection (1 paper, 2014). "We found that genes such as IL6, Sh3gl3, and Atxn10, which had previously been associated with different phenotypic outcomes in response to IAV infection, also expressed different isoforms in response to SARS-CoV infection." (PMID 24902603, 2014).
spinal muscular atrophy (1 paper, 2013). A motor neuron disease that affect the muscles, and characterized by muscle weakness and atrophy resulting from progressive degeneration and irreversible loss of the anterior horn cells in the spinal cord (i.e., lower motor neurons) and the brain stem nuclei. "SMN1 deficiency in lymphoblasts from patients with spinal muscular atrophy led to splicing defects in U12-type introns from the ATXN10 gene." (PMID 23752268, 2013). "Homozygous deletion of SMN1 was shown to be accompanied by intron retention in the U12-type intron from the ATXN10 and Thoc2 genes in lymphoblasts derived from patients with spinal muscular atrophy." (PMID 23752268, 2013).
neurological diseases (7 papers, 2011 to 2026). "By studying this dataset, we identified a new CMA substrate, Ataxin-10, a protein involved in a neurologic disorder." (PMID 42142583, 2026).
neurodegenerative disease (4 papers, 2009 to 2022). A disorder of the central nervous system characterized by gradual and progressive loss of neural tissue and neurologic function. "Ataxin-10 is involved in neurodegeneration and maybe associated with neurodegenerative diseases." (PMID 24098440, 2013).
adenocarcinoma (1 paper, 2022). A common cancer characterized by the presence of malignant glandular cells. "Markers such as TNFα, IL-6, and Ataxin-10 were observed to be elevated in cardiac tissue of colon-26 (C26) adenocarcinoma mice." (PMID 35326491, 2022).
genetic disorder (1 paper, 2022). "SCA10 was the first human genetic disorder discovered to be caused by an expanded intronic pentanucleotide (ATTCT) repeat in intron 9 of the ATXN10 gene on chromosome 22q13.3." (PMID 36199580, 2022).
infection (1 paper, 2021). The state of being infected such as from the introduction of a foreign agent such as serum, vaccine, antigenic substance or organism. "Per bin, the intron counts of the infection-induced genes IFIT2, OAS2, CCL5, IL6, NFKBIA, and TNF are shown, along with ATXN10 as control." (PMID 33585804, 2021).
inflammation (1 paper, 2021). Aberrant reaction of the microcirculation characterized by movement of fluid and leukocytes from the blood into extravascular tissues. "In summary, our data demonstrate a novel role for Ataxin-10 in the regulation of TNF-α-induced endothelial inflammation via suppressing IRF-1." (PMID 34858081, 2021).
tumour (1 paper, 2011).
ATXN10 also shares sentences with these, for which no sentence is quoted: epilepsy (8 papers); amyotrophic lateral sclerosis (6); myotonic dystrophy type 2 (6); cerebellar ataxia (5); Friedreich ataxia (4); frontotemporal dementia (4); fragile X syndrome (3); autosomal recessive cerebellar ataxia (2); dementia (2); fragile X-associated tremor/ataxia syndrome (2); myotonic dystrophy type 1 (2); acquired ataxia (1); Action tremor (1); ataxia telangiectasia (1); autosomal dominant disease (1); bacterial infection (1); Boucher–Neuhauser Syndrome (1); breast carcinoma (1); cancer (1); Cerebellar atrophy (1); cerebellar degeneration (1); colon (1); essential tremor (1); facioscapulohumeral muscular dystrophy (1); Fuchs endothelial corneal dystrophy (1); Gait ataxia (1); glioma (1); hereditary ataxia (1); hereditary cerebellar ataxia (1); Hyperreflexia (1).
A further 13 diseases each share a sentence with ATXN10 in 1 paper.